CD68 (CD68 molecule)
Diseases named in the same sentence as CD68 in open-access papers (continued):
Sharing a sentence is not in itself a finding about the gene and the disease.
tumor (continued). "This implied that the CD68 and PD-1 complex might be stabilized through the binding of LAMP-like and IgV domains, enhancing the tumor immune inhibition function of PD-1." (PMID 34079767, 2021). "PD-L1 co-localisation with CD68 was only associated with high TILs (p < 0.001), whilst with FOXP3, it was associated with smaller tumours (p = 0.028), negative nodal status (p = 0.009) and high sTILs (p = 0.017)." (PMID 34732817, 2021). "CD68 and CD163 were occasionally positive in tumor tissues from some patients." (PMID 34458140, 2021). "This adverse prognostic association of CD68 + CLS-B was independent of BMI and tumour factors such as grade, stage and hormone receptor status, but was attenuated when adjusted for metabolic factors." (PMID 34294716, 2021). "Indeed, DCs acquire an immunosuppressive phenotype (CD14+/CD16+/CD68+/CD124+/CD209+; PD-L1 overexpression), becoming incapable of cross-presenting tumor antigens to T cells and inhibiting the T cell response." (PMID 34945784, 2021). "In contrast, neither CD68+ ov-TAMs, CD163+ ov-TAMs nor the ratio of CD68+/CD163+ ov-TAMs was associated with age, FIGO stage, residual tumor or chemosensitivity." (PMID 34677277, 2021). "Despite of the small changes in the CSF cytokine profile, a negative correlation was found between the number of CD68+ macrophages in the tumor tissue and the inflammatory cluster as revealed by our principal component analysis." (PMID 34654395, 2021). "Substantially elevated levels of IL‐33 and CD206 but not CD68 were observed in the tumour tissue samples than the non‐tumour tissue samples." (PMID 33305406, 2021). "However, CD68+ TAMs that are thought to be partly derived from TAM1s, when with CD8+ TILs, are suggested to be involved in effective anti-tumor immunity." (PMID 34089486, 2021). "In addition to the cluster of “macrophage-high” and “macrophage-low” tumors, a subset of tumors shows increased expression of CD68 and CD163 in the stroma, but low expression of CD163 in tumor nests and MHCII on tumor cells." (PMID 34200100, 2021). "In addition, CD68 (macrophage) is highly correlated to antigen-presentation responses (HLA-DRA, r = 0.71 and 0.60 in normal and tumor tissues, respectively) and moderately correlated to GZMB (r = 0.54 and 0.47 in normal and tumor tissues, respectively)." (PMID 34758832, 2021). "On the other hand, numerous CD68+ macrophages were observed both intra- and around the tumor of the patient with PD, but no PD-L1 expression was detected." (PMID 33946835, 2021). "The increased presence of CD68+ cells and inflammatory markers in BRAF+ tumours could indicate that BRAF status may play a role in determining the response of patients to immunotherapies or immunogenic treatments." (PMID 32843682, 2020). "Thus, we examined the M2 macrophage percentage (CD206/CD68) in HCC peri- and intra-tumor tissue using immunohistochemical staining." (PMID 32013887, 2020). "Next, enrichment in the GC tissues was also revealed that the ratio of CD68+ macrophages in the GC tissues was greater than that in the tumor-adjacent and non-cancerous stomach tissues." (PMID 33330451, 2020). "Generally, tumor cells did not express — but macrophages stained by CD68 did express— PD-L1 in most of the 70 patients with PCNSL." (PMID 32248797, 2020). "Simply, it is defined by evaluating the tumor immune microenvironment through various immune markers such as CD3, CD8, CD68, PD1, and PD-L1 in tissue sections in lung and colorectal cancer, and potentially offers a relatively uniform parameter of prognostic and predictive values." (PMID 31996725, 2020). "As a whole, the CD68+ PD-L1+ macrophages and CD8+ PD-1High T cells may cooperatively play a role in inhibiting anti-tumor immunity." (PMID 33228682, 2020). "All 33 tumor samples were stained and evaluated for the immune markers CD3, CD8, and CD68." (PMID 32181153, 2020).
tumor (continued). "The tumor itself was divided into two distinct CNs: CN-2, mainly comprised of tumor cells (“bulk tumor”), and CN-6, which contained tumor cells as well as CD11c+ DCs, CD68+ macrophages, T cell subsets, and other immune and non-immune CTs (“tumor boundary”)." (PMID 32763154, 2020). "A case-by-case analysis showed a positive correlation between the stromal CD68 counts and total tumor CD163 counts, but not with the total tumor iNOS counts." (PMID 32824692, 2020). "The CD68+ PD-L1+ macrophages and CD8+ PD-1High T cells may cooperatively play a role in inhibiting anti-tumor immunity." (PMID 33228682, 2020). "In the same cohort high CD163+/CD68+ ratio in the tumor front, but not in tumor stroma, was closely correlated with enhanced lymphovascular invasion, tumor invasion, and TNM stage as well as recurrence-free survival (RFS) and OS of patients with CRC." (PMID 33194645, 2020). "The combination of either CD4 or CD68 with CSF1R predicted a more favorable prognosis (p < 0.01), suggesting that coordinated interaction between tumor antigen-specific CD4+ Th1 cells and CSF1R might participate in macrophage polarization toward CD68+ M1 TAM." (PMID 32850346, 2020). "Intratumoral CD68+ cells were significantly higher in PHEOs with regular or normal histological patterns than those not (p = 0.0370) and inversely correlated with tumor size (p = 0.0457)." (PMID 33244312, 2020). "Having shown the effect of CD68+ and CD163+ macrophage infiltration, we next observed if the number of iNOS+ or arginase+ cells independently correlated to pathological features of the tumour." (PMID 32843682, 2020). "We found CD68+, CD163+, and CD206+ TAMs distributed in both tumor stroma and tumor islets." (PMID 32884895, 2020). "The study was based on 107 TNC cases operated on at Dokkyo Medical University Hospital using the pan-macrophage marker CD68 and the M2 macrophage marker CD163 in the tumor stroma (TS) and tumor nest (TN), respectively, and examined the clinicopathological significance." (PMID 32607685, 2020). "Protumorigenic TAMs such as those that can be identified by dual staining with CD68 and CD163 are known to promote tumor cell proliferation, angiogenesis, invasion, and metastasis as well as to suppress T-cell–mediated antitumor immune responses through paracrine mechanisms." (PMID 32190817, 2020). "To test the capacity of liposomal clodronate for CD68+ cell depletion, we administered the compound to healthy mice without a tumor burden (n = 4) and found the robust ablation of CD68+ splenic macrophages." (PMID 32698524, 2020). "The density of CD8+ and CD45RO+ cells were significantly higher in stroma than in tumour epithelium (p = 0.005 and p = 0.004, respectively; Welch’s t test), but not significantly different for CD68+ cells." (PMID 32249277, 2020). "Kim SJ and Ham JS analyzed the serum cytokines and CD68- and CD163- positive macrophage in tumor tissue of 37 AITL patients after CHOP chemotherapy, and found that high IL-10 and M2 macrophage tissue infiltration all indicated low OS and poor response to treatment." (PMID 33154947, 2020). "Further flow cytometry analysis of splenic lymphocyte showed that Kejinyan decoction upregulated M1 macrophages and downregulated M2 macrophages, while the total level of macrophages changed little, which was verified by detection of CD68, F4/80, CD206, and CD86 in tumor tissue section." (PMID 32943999, 2020). "Immunohistochemical scores of CD68 and CD163 were statistically related to bulky disease (p value = 0.005 for both), tumor stage (p value = 0.02 for both), International Prognostic Score (IPS) (p value = 0.04 and 0.02 respectively), and the overall response rate (ORR) (p value = 0.001)." (PMID 32372254, 2020). "Intra-epithelial CD8+ and CD45RO+ densities were weakly correlated with the purity/tumour fraction of the sample (R2 = 0.17, p = 0.003 and R2 = 0.16, p = 0.006), but CD68+ epithelial density was not." (PMID 32249277, 2020).
tumor (continued). "Further, in the resected tumor specimen at 6 weeks following RT/HTRT, significantly higher number of CD4+ cells were evident in the RT-treated part whereas significantly higher number of macrophages (CD68+) were observed in the part treated with HTRT." (PMID 32596144, 2020). "We next analysed all the genes that were mutated in our samples and correlated the mutated genes with the corresponding biological information, including tumour grade, degree of differentiation and invasiveness, proliferation index and extent of immune cell infiltrate (CD45+, CD3+ and CD68+ cells)." (PMID 33168804, 2020). "The most notable finding was that PD-L1 expression in CD68-positive cells (macrophages) rather than in tumour cells was integral to determining progression-free survival, overall survival, and treatment responses in melanoma patients." (PMID 32917035, 2020). "Double immunostainings for CD68 and CD163 antigens were applied to pre-RT tissue samples from four locations: central tumour (CT), invasive front (IF), normal tissue taken from tumour proximity (prox) and normal tissue that was sampled distant from the tumour (dist)." (PMID 32075091, 2020). "There was a marked dose-dependent trend towards reduced numbers of CD68+ luminal macrophages in areas of in situ tumor growth, but this was not seen in areas of invasive growth." (PMID 32190817, 2020). "The main cell type present was CD68+ macrophages, which were easily misconstrued as negative tumor cells rather than an inadequate sample using brightfield assessment." (PMID 32365629, 2020). "CD68+ macrophages are usually activated during antigen presentation and inflammatory responses, while CD163+ macrophages have a large number of anti-inflammatory cytokines that contribute to immunosuppression and promote tumor development." (PMID 32528967, 2020). "Unlike tumor infiltrating T cells, CD68+, CD163+ TAMs and CD20+ TILs all failed to be prognostic indicators for OS and RFS." (PMID 30885276, 2019). "Baseline tumor biopsies from 196 patients in the NEOZOTAC trial were analyzed for CD8 (cytotoxic T-cells), FoxP3 (regulatory T-cells), CD68 (macrophages), and HLA class I (HCA2/HC10) expression by immunohistochemistry and subsequently related to pCR and disease-free survival (DFS)." (PMID 30868392, 2019). "Here, the tumor mass surrounded by a lymph follicle showed high proportion of PanCK+ neoplastic cells as well as high α-SMA expression and peripheral accumulation of CD68+ cells." (PMID 30899426, 2019). "Our data showed that the percentage of tissues with RGC-32+CD68+ cells was higher than those in normal tissue, reflecting that RGC-32 expression might be regulated by tumor microenvironment." (PMID 31601783, 2019). "Although the number of HLA-DR+CD68+ cells, defined as M1 macrophages population, did not markedly change during tumor development in this study, and more activated M1 macrophages were detected in the pathological tissue than in para-carcinoma tissue." (PMID 30483821, 2019). "While high CD68++CD163+ TAM density proximal to the tumor correlated with improved survival in univariate analysis, this was not confirmed in a multivariate model incorporating known prognostic clinical parameters (e.g., age, tumor stage)." (PMID 31477692, 2019). "We found that tumor CD47 expression (HR = 1.703; p = 0.038), CD68+ M (HR = 1.853; p = 0.012), CD163+ M2 (HR = 1.898; p = 0.014), tumor diameter (HR = 1.626; p = 0.047), grade (HR = 1.745; p = 0.011), and N stage (HR = 1.831; p < 0.001) were independent factors associated with OS." (PMID 31771616, 2019). "Immunohistochemical staining was performed in six PSPs, and we found that some tumor cells were immunopositive for epithelial membrane antigen (EMA) (3/6), thyroid transcription factor‐1 (TTF‐1) (6/6), vimentin (2/6), CD68 (2/6) and cytoskeleton 7 (CK‐7) (4/6)." (PMID 31131992, 2019). "In the tumour-free CTR area, IL-35 correlated with CD68+ macrophages." (PMID 30956278, 2019).
tumor (continued). "The tumor cells were positive for CD68, NSE, S-100, and CD163 expression but negative for GFAP, Syn, and CD123 expression." (PMID 31023279, 2019). "When correlation of larger tumor samples versus central and peripheral tumor biopsies were separately analyzed for macrophage marker CD68, their correlation was not statistically significant." (PMID 31772388, 2019). "The tumour cells were positive to vimentin and CD68, and negative to desmin, SMA, S100 protein, EMA, cytokeratins AE1/AE3, CD117, and CD34 antibodies." (PMID 31773099, 2019). "Notably, our data revealed increased M2 macrophage markers, CD68 and CD163 and Arginase (Arg), immunoreactivity at the tumor stromal interface of PKTP PDAC, compared with the PKP model." (PMID 31109321, 2019). "Also, HLA-1 low-expressing tumor areas appeared to frequently be surrounded by a greater number of CD4+FOXP3+ (regulatory T cells) and a lower number of CD68+ (likely macrophages) immune cells relative to HLA-1 high-expressing tumor regions of the same TME." (PMID 31166985, 2019). "Here, we found that the number of infiltrating CD206+CD68+ macrophages did not alter between benign tissue and tumor tissue in CRC patients." (PMID 31602788, 2019). "We used multiplexed IHC and multispectral imaging to score five different tumour-infiltrating immune cells in CRC using well-established markers (CD8+ cytotoxic T lymphocytes, FOXP3+ T regulatory cells, CD20+ B lymphocytes, CD68+ macrophages, and CD66b+ neutrophils)." (PMID 31882709, 2019). "The expression level of CCR6, but not CD68, was significantly higher in the ≥T2, N+, and N+ samples than in the T1 localized small tumor samples." (PMID 31905918, 2019). "Immunohistochemical analysis using an antibody specific to the CD68+ human epitope depicted TAMs in patient tumor alone and not in subcutaneous PDX and PDOX." (PMID 31732509, 2019). "In a single region of interest, among other cell types, tumor cells (Keratin+), T-helper cells (CD3+CD4+), cytotoxic T cells (CD3+CD8+), regulatory T cells (CD3+FOXP3+), HLA-DR+ macrophages (CD68+HLA-DR+), CD163+ macrophages (CD68+CD163+), and CD11c+ macrophages (CD68+CD11c+), were identified." (PMID 31736961, 2019). "Notably, systemic CpG-C administration did not affect infiltration of T cells (i.e., CD4+) or monocytes (i.e., CD68+) into the brain, or the number of GFP+ cells (i.e., monocytes/microglia) evident in the brain 24 hours following administration of tumor cells." (PMID 30921319, 2019). "In contrast, the tumor cells express high levels of CD68 but no Iba1 protein (CD68high and Iba1(−))." (PMID 29346317, 2018). "Tissue slides from sentinel node biopsies and tumor resections from thirty women who underwent sentinel node biopsy with invasive breast cancer resection were dual stained for CD3/IL-10, CD3/IFN-gamma or triple stained for CD3/CD20/CD68." (PMID 30400835, 2018). "Perhaps the most striking finding was that, using a CD68 specific compartment marker measurement, we found that PD-L1 expression in macrophages and not in tumor was a predictive marker for PFS, OS and response." (PMID 30400835, 2018). "In addition to PD-L1 staining, tumor-infiltrating immune cells were identified by IHC as CD3+ tumor infiltrating lymphocytes (TIL) and CD68+ tumor infiltrating myeloid cells (TIM)." (PMID 29721192, 2018). "Targets were measured in CK+ tumor cells, CD68+ macrophages and the non-CK stromal compartment, then split by the median." (PMID 30400835, 2018). "We detected a number of CD68+ macrophages in the spleen of both tumor-bearing HSC-NOG-hIL-6 Tg and HSC-NOG non-Tg mice, with greater numbers detected in HSC-NOG-hIL-6 Tg mice than in HSC-NOG non-Tg mice." (PMID 29456539, 2018). "High‐level IL‐8 expression in tumor stroma was correlated with high frequent lymph node metastasis, high density of tumor CD68 but not CD163 positive macrophages." (PMID 30311406, 2018).
tumor (continued). "Few CD68+ macrophages infiltrated the tumor in HSC-NOG non-Tg mice, whereas an abundance of CD68+ macrophages infiltrated the tumor in HSC-NOG-hIL-6 Tg mice." (PMID 29456539, 2018). "What is more, IL‐8 expression level in tumor stroma by immunohistochemical analysis was related to lymph node metastasis, the number of tumor CD68 but not CD163 positive macrophages and patient outcome." (PMID 30311406, 2018). "On the contrary, surface density of CD68 and CD11c+ cells was 2.5 higher in TLS than in tumor." (PMID 30038899, 2018). "In contrast, OS was significantly shorter for patients with high PD-L1 but low CMTM6 expression in stroma (3m vs. 14m, p = 0.02) or CD68 (6m vs. 15m, p = 0.02), but not in the tumor cell compartment (21m vs. 12m, p = 0.80)." (PMID 30400835, 2018). "More importantly, there was also a significant correlation between IL‐8 expression level and the number of tumor CD68 positive but not CD163 positive macrophages, and we also found that IL‐8 and CD68 were coexpressed in PDAC tissue." (PMID 30311406, 2018). "Our observations revealed that PD-L1 staining co-localized with area showing marked positivity for CD3+ T-lymphocytes and CD68+ macrophages, while lack of co-localization with tumor cells is highlighted by nuclear staining of myogenin in RMS tissue." (PMID 29898687, 2018). "These markers (Foxp3, CD68, and CD163) were expressed on immune cells in the tumor stroma." (PMID 29506555, 2018). "An average 70% of CD68+ and CD163+ pixels were between 0 and 20 microns from the tumor edge." (PMID 30619287, 2018). "Moreover, to better define PD-L1 protein expression in the immune component (infiltrating or surrounding the tumor), a panel of linage specific antibodies (CD3, CD68, CD20, CD163 CD56, CD57) was utilized, on samples with available material." (PMID 29898687, 2018). "A similar result was obtained when a macrophage signature comprising a subset of eight widely used markers (CD14, CD105, CD11b, CD68, CD93, CD33, IL-4R and CD163) for the mononuclear phagocyte system was used to identify tumours highly infiltrated by macrophages." (PMID 29921315, 2018). "TAMs are known to have a role in tumor angiogenesis; therefore, we assumed that TAMs can affect the increase in nCBV values, which can be simultaneously correlated with TAM markers (e.g., CD11b, CD68 and CSF1R)." (PMID 30375429, 2018). "Hence, further studies correlating CD68 and TIL levels in ER-positive/HER2-negative cancer will shed light on the tumor-immune interaction in this subset." (PMID 29573739, 2018). "We subsequently conducted immunohistochemical analyses on formalin-fixed tumor slices and recorded an increased presence of CD45+/ CD68+ cells having an elevated expression of Arg-1 and TGF-β1 in tumors from gemcitabine-treated mice, compared to those treated with vehicle only." (PMID 30097594, 2018). "TAMs, including all CD68+ macrophages, as well as CD68+/CD163+ cells were found at the stroma and perivascular areas or filling ductal-like structures and inter-epithelial cell gaps within the tumor islets." (PMID 30558648, 2018). "In order to exclude that vimentin+ cells in tumor areas represented infiltrating non-tumor cells, selected tumor specimens were stained with vimentin- and either CD31- (endothelial cells), CD68- (monocytes/macrophages), or CD90-specific antibodies (fibroblasts), respectively." (PMID 30275505, 2018). "e Representative IHC staining of B3GALNT2, CD68, and CD206 in human HCC tumor tissues." (PMID 29618368, 2018). "CD68+ macrophage-like cells were usually seen scattered between the tumor cell nests (data not shown)." (PMID 28642820, 2017). "CD68 is always used as a pan-Mφ marker, while CD204 and CD169 might represent different Mφ subpopulations with pro- or anti-tumor functions during tumor progression." (PMID 28202073, 2017). "CD68+/pSTAT1+ double positive cells were found in the tumor debulking group whereas no pSTAT1+ cells were observed in the non-debulking group." (PMID 28076333, 2017).